URB2 (URB2 ribosome biogenesis homolog)
Synonyms: KIAA0133; NPA2; NET10
Tractability: PROTAC: ubiquitination databases record sites on it; its protein half-life has been measured.
Gene: Protein-coding gene on chromosome 1 (229,625,855 to 229,660,887, forward strand). Ensembl gene ENSG00000135763.
Subcellular location: Nucleus, nucleolus
Subcellular location (Human Protein Atlas): Nucleoli
Gene Ontology:
Biological process: ribosome biogenesis
Cellular component: midbody; nucleolus
Genetic constraint (gnomAD): Loss-of-function variants: 86 observed, 130.92 expected, observed/expected ratio (o/e) 0.66, 90% interval 0.55 to 0.79. The upper end of that interval is the gene's LOEUF score, 0.79, which puts it in group 3 of 6, group 1 being the genes least tolerant of losing a copy. Missense variants: 1,745 observed, 1,901.4 expected, observed/expected ratio (o/e) 0.92, 90% interval 0.88 to 0.95. Synonymous variants: 743 observed, 786.14 expected, observed/expected ratio (o/e) 0.95, 90% interval 0.89 to 1.
Homologues: Orthologues: chimpanzee URB2 (99% identical), macaque URB2 (94% identical), rabbit URB2 (81% identical), dog URB2 (80% identical), pig URB2 (75% identical), rat Urb2 (73% identical), mouse Urb2 (72% identical), tropical clawed frog urb2 (42% identical), zebrafish urb2 (36% identical).
Diseases named in the same sentence as URB2 in open-access papers:
URB2 is named in the same sentence as 13 diseases in open-access papers, as found by Europe PMC text mining. Sharing a sentence is not in itself a finding about the gene and the disease. The quoted sentences say what the papers report.
familial partial lipodystrophy (1 paper, 2015). "The precise mechanistic role of URB2 is still poorly understood, but conditions caused by defects in lamin genes (laminopathies), including familial partial lipodystrophy, can cause loss of adipose tissue, insulin resistance, and metabolic syndrome." (PMID 25625282, 2015).
glioma (1 paper, 2023). A benign or malignant brain and spinal cord tumor that arises from glial cells (astrocytes, oligodendrocytes, ependymal cells). "More importantly, a close relationship between immunity and URB2 was found, which is preliminary and underling evidence that the immune response contributes to glioma progression, suggesting novel approaches to immune therapy for glioma." (PMID 37033651, 2023). "Univariate Cox analysis indicated that PRS type, histology, 1p/19q status, age, grade, IDH mutation, Chemo status, and URB2 expression were significantly related to OS in glioma patients." (PMID 37033651, 2023). "As is shown in figures, URB2 was expressed in all types of annotated cells, including immune cells, which partially supports the close association of URB2 with immunity in glioma." (PMID 37033651, 2023). "Several immune cells associated with URB2 in gliomas were expressed." (PMID 37033651, 2023). "Furthermore, several immune checkpoints that have been implicated in gliomas were evaluated and associated with URB2 using immune checkpoint analysis." (PMID 37033651, 2023). "In the CGGA database, low expression of URB2 has a strong correlation with better pathological stage, histological grade, and longer OS in glioma patients." (PMID 37033651, 2023). "Using CellMiner, we further found two drugs (fludarabine and XL-147) correlated with URB2, which means that inhibitors of these two drugs can be potential treatment drugs for immune therapy in glioma." (PMID 37033651, 2023). "To demonstrate the difference in the protein expression level of URB2 between normal brain tissues and glioma, we further validated the CPTAC database." (PMID 37033651, 2023). "URB2 expression in patients with gliomas was incorporated with nine clinicopathological variables to generate a risk score, including IDH mutation status, grade, sex, histology, age, radio status, Chemo status, PRS type, and 1p/19q codeletion status." (PMID 37033651, 2023). "To further explore the role of URB2 in the progression of glioma, we downregulated the expression of URB2 in U87 and U251 cells." (PMID 37033651, 2023). "ROC analysis was also performed to determine the prognostic value of URB2 expression in gliomas, in which the AUC of URB2 expression was 0.856 (1-year), 0.885 (3-year), and 0.881 (5-year), and the C-index was 0.8009." (PMID 37033651, 2023). "Most importantly, this is the first study of the prognostic role of URB2 and the immunological role of URB2 in tumorigenesis and progression in glioma." (PMID 37033651, 2023). "We further found two drugs (fludarabine and XL-147) with a correlation with URB2, which means that inhibitors of these two drugs can be potential treatment drugs for immune therapy in glioma." (PMID 37033651, 2023). "In CPTAP samples, URB2 protein expression was much higher in gliomas, and similar results were found in glioma patients of different sexes, ages and weights." (PMID 37033651, 2023). "We further performed GSEA between tissues with different URB2 expression levels to explore the role of URB2 in glioma pathogenesis." (PMID 37033651, 2023). "In our research, we demonstrated that the expression of URB2 is higher in glioma than adjacent normal tissue, an indication that OS may be poor." (PMID 37033651, 2023). "Then, we also tested the expression of URB2 in low-grade glioma (LGG) and high-grade glioma (HGG)." (PMID 37033651, 2023). "Then, we evaluated the StromalScore, ImmuneScore, and ESTIMATEScore to determine whether URB2 expression correlates with the microenvironment around gliomas." (PMID 37033651, 2023). "Therefore, URB2 was evaluated in glioma in terms of prognostic and immunological values in the present study." (PMID 37033651, 2023). "Therefore, we investigated the predictive value of URB2 in glioma and elucidated its relationship with immunity in this study." (PMID 37033651, 2023). "Together, our research indicated that URB2 plays an oncogenic role in gliomas." (PMID 37033651, 2023).
glioma (continued). "According to Cox regression analyses, URB2 was considered an independent factor for glioma." (PMID 37033651, 2023). "Furthermore, we revealed a close relationship between immunity and URB2, which suggests a new approach for the immunotherapy of glioma." (PMID 37033651, 2023). "Furthermore, we not only identified the correlation between URB2 and immunity through multiple perspectives but also identified immunotherapeutic agents targeting URB2 in glioma." (PMID 37033651, 2023). "Thus, we analyzed the correlation between MSI and the expression of URB2 in glioma." (PMID 37033651, 2023). "Our study constructed a nomogram for predicting the OS of glioma patients according to the CGGA dataset based on ten independent prognostic factors, including 1p/19q codeletion status, PRS type, Radio status, Histology, Chemo status, Gender, Age, IDH mutation status, Grade, and URB2." (PMID 37033651, 2023). "Cox regression analysis revealed that URB2 may be a predictor for prognosis in glioma patients." (PMID 37033651, 2023). "However, the prognostic role of URB2 and the specific roles of URB2 in tumorigenesis and progression in glioma have not been reported." (PMID 37033651, 2023). "The specific role of URB2 in glioma has not been fully investigated experimentally." (PMID 37033651, 2023). "Thus, in gliomas, TMB may play an important role in URB2 function." (PMID 37033651, 2023).
tumor (3 papers, 2022 to 2025). "With regard to the relationship between immunity and URB2, we demonstrate that the expression of URB2 is significantly associated with immune cells, tumor immune microenvironments (TIMs), and immune checkpoint molecules (ICMs)." (PMID 37033651, 2023). "Moreover, we revealed that URB2 expression was strongly associated with the tumor immune microenvironment, immune cell infiltration, immune checkpoint molecules, and immune cells." (PMID 37033651, 2023). "To better understand the immunological correlates of URB2, we evaluated the relationship between URB2 expression and prognosis related to immune infiltration and the tumor microenvironment." (PMID 37033651, 2023). "The results suggested that, the high expression of C1orf74, HK2, SLC22A3, SNX10 and URB2 and Neutrophils, as well as the low expression of RASSF5 and CD8+ T cells was related to the poor prognosis of CC patients, which might serve as the key prognostic biomarkers of tumor." (PMID 36354693, 2022).
URB2 also shares sentences with these, for which no sentence is quoted: cancer (1 paper); depression (1); glioblastoma multiforme (1); infection (1); Insulin resistance (1); laminopathies (1); metabolic syndrome (1); rheumatoid arthritis (1); schizophrenia (1); type 2 diabetes (1).